CD44 (CD44 molecule (IN blood group))
Diseases named in the same sentence as CD44 in open-access papers (continued):
Sharing a sentence is not in itself a finding about the gene and the disease.
pancreatic cancer (continued). "The overexpression of CD44 was shown to be associated with aggressive malignant attitudes, cell migration, and distance metastasis, therefore with poor overall survival in patients with pancreatic cancer." (PMID 33672926, 2021). "Our results suggest that Has2/CD44 signaling might be a valid target for patients with TGIF1-deficient pancreatic cancer." (PMID 31109321, 2019). "The most widely studied CD44 variant form in pancreatic cancer is CD44v6." (PMID 29747682, 2018). "CD44 has been implicated in the MDR of pancreatic cancer cells." (PMID 28611316, 2017). "Therefore, among all CD44 variants, CD44v6+/CD44s− was an independent risk factor affecting the OS rate of pancreatic carcinoma patients." (PMID 24708709, 2014). "In the present work, we have used the γ-secretase inhibitor IX (GSI) to show that the Notch signalling pathway contributes to the acquisition of epithelial mesenchymal transition (EMT) and is associated with the maintenance of pancreatic tumor initiating CD44+/EpCAM+ cells." (PMID 23094026, 2012). "Similar roles for the SPP1-CD44 axis have been observed in other cancers, such as pancreatic cancer, where SPP1 secreted by cancer-associated fibroblasts (CAFs) enhances stem cell characteristics through CD44 interaction." (PMID 40076844, 2025). "It was reported that high PD-L1 expression in pancreatic cancer tissues with high levels of CD44+/CD133+ CSCs predicts an unfavorable prognosis of pancreatic cancer." (PMID 39990669, 2025). "Intriguingly, Chen and colleagues reported that high levels of CD44, another stem cell marker associated with an invasive phenotype similar to CD90, are also linked to gemcitabine resistance in pancreatic cancer cells and preclinical models." (PMID 40507785, 2025). "In the mouse PC, H3K4me3 has been implicated in promoting pancreatic tumor growth and progression through the activation of the osteopontin (OPN)-CD44 axis, which in turn promotes immune evasion in pancreatic cancer." (PMID 38305306, 2025). "Clinical studies for pancreatic cancer targeting CD44 or CXCR4 have encountered toxicity, suboptimal target engagement, or inadequate penetration into thick stromal environments." (PMID 41439922, 2025). "Utilizing XGBoost and RF, we pinpointed 10 genes closely related to pancreatic cancer, culminating in the identification of RAP1GDS1, TOP2A, ADK, POLL, CD44, and CD4 as pivotal genes linked to hypoxia in pancreatitis." (PMID 40787634, 2025). "As expected, these nanocarriers demonstrated targeted, rapid release under intracellular conditions and showed increased selectivity for CD44-positive pancreatic cancer cells." (PMID 39766133, 2024). "The likelihood of off-target effects of HA-displaying NPs is minimized due to several factors: pancreatic cancer cells express higher levels of CD44, while normal tissues have lower CD44 expression." (PMID 39458615, 2024). "This research shows the potential to serve as the foundation for investigating the efficacy of immunotherapy in reducing CD44-expressing CSCs in pancreatic cancer, potentially enhancing patient outcomes." (PMID 39148690, 2024). "In pancreatic cancer, CD44 is involved in tumorigenicity, clinicopathological features, and invasiveness." (PMID 38783892, 2024). "We have previously reported that the CD44-expressing pancreatic cancer cell line MIA PaCa-2 binds and internalizes HA with high efficiency." (PMID 39458615, 2024). "In another study, researchers coated IONPs with anti-CD44 antibodies to specifically target CD44-positive pancreatic cancer cells, facilitating gemcitabine delivery to induce cell death." (PMID 39766133, 2024). "And recent research demonstrated that high expression of CD44 is highly correlated with increased aggressiveness of pancreatic cancer and increased gemcitabine resistance to chemo chemicals." (PMID 37333498, 2023).
pancreatic cancer (continued). "In conclusion, cancer stem-like cells play a pivotal role in acquiring multidrug resistance in pancreatic cancer; CD44+ cells in particular, which repopulate after chemotherapy, were responsible for the chemoresistance mediated by ABCB1." (PMID 37108495, 2023). "Contrary to the studies above, Yan and colleagues show that KLF4 and CD44 expression is mutually exclusive, specifically within human metastatic pancreatic tumors and in autochthonous mouse models of PDAC." (PMID 37239940, 2023). "CD133+/CD44+/CD24+/ESA+ PCSCs isolated from human primary pancreatic tumor were orthotopically injected into NOD/SCID/IL2R gamma mice." (PMID 36776295, 2023). "Here, we discovered that silencing CDK1 significantly inhibited a subgroup of CD44+/CD24+ cells as well as the tumor stemness of pancreatic cancer." (PMID 37743465, 2023). "CD44 + CD24 + ESA + pancreatic cancer cells have been reported to exhibit significant resistance to GEM and radiation and contribute to pancreatic cancer recurrence and metastasis." (PMID 37737908, 2023). "A subpopulation of pancreatic cancer cells showing CD44+CD24+ESA+ have been proven to possess stem cell-like properties of self-renewal and the ability to produce differentiated progeny." (PMID 37108495, 2023). "The Cancer Genome Atlas (TCGA) data analysis revealed that NT5E gene expression was strongly correlated with CD44 and ROCK1/ROCK2 gene expressions in pancreatic tumors, suggesting a link between CD73 and loss of epithelial features." (PMID 37851808, 2023). "In pancreatic cancer, the crucial role of CD44/TGFβ receptors (TβRI and TβRII) signalling is well admitted not only in epithelial-to-mesenchymal transition but also in the earlier ADM step." (PMID 38098486, 2023). "In pancreatic cancer, although CD44+ cells themselves were more tumorigenic than CD44− cells, CD44+/CD24+/ESA+ cells had more stem cell-like characteristics than CD44−/CD24−/ESA− cells." (PMID 37108495, 2023). "Although CD44 itself is not sufficient to define all the phenotypes of CSCs, it appears obvious that CD44 is one of the important CSC markers in pancreatic cancer." (PMID 37108495, 2023). "Putative CSCs have been identified in pancreatic cancer based on the expression of the three surface markers CD44, CD24, and epithelial specific antigen (ESA)." (PMID 37108495, 2023). "They co-localized with the cancer stem cell marker CD44, promoting tumorigenesis and the growth of pancreatic cancer." (PMID 36012604, 2022). "Downstream molecular targets of CD44 isoforms that mediate pancreatic cancer chemoresistance need to be identified." (PMID 35846884, 2022). "In vitro experiment by our group demonstrated that the inhibition of B7-H4 increased cell-cell adhesion, decreased the formation of pseudopodia, increased the expression of E-cadherin, and decreased the expression of vimentin and CD44 in pancreatic cancer." (PMID 36217128, 2022). "Inhibition of cluster of differentiation 44 (CD44), a pancreatic cancer stem cell (CSC) marker, is a potential treatment for pancreatic ductal adenocarcinoma (PDAC)." (PMID 36605595, 2022). "We found that CD44 high-expressing pancreatic cancer cells show predominantly CD44s isoform with an EMT phenotype, were highly invasive, and rapidly developed resistance to gemcitabine in vivo." (PMID 35931675, 2022). "The in vitro pancreatic cancer cell line data suggests that IGF1R signaling is required to induce a phenotypic switch of cells that possess low CD44 expression to one that shows a high level of CD44 expression with CD44s being the predominant isoform." (PMID 35931675, 2022). "Here, we studied the function of CD44 in pancreatic cancer progression and prognosis and found that the expression of one splicing variant, CD44V3, instead of CD44, was significantly increased in tumor tissues, and its level correlated with poor prognosis." (PMID 36292918, 2022).
pancreatic cancer (continued). "Given that CDCA8 promoted the proliferation and migration of pancreatic cancer cells in vitro and in vivo, we next sought to explore the underlying mechanisms by focusing on the relationship between CDCA8 and CD44 expression." (PMID 36358852, 2022). "Next, we examined CD44 expression in normal and different stages of pancreatic tumor tissues using the Kaplan–Meier Plotter." (PMID 36292918, 2022). "In pancreatic cancer, CSCs were first reported in 2007 as a subpopulation of CD44(+)/CD24(+)/ESA(+) or CD133(+)/CXCR4(+) cancer cells, and many CSCs have been identified using these three methods." (PMID 35629168, 2022). "Of note, long term gemcitabine resistant pancreatic cancer cells detected increased expression of CD44 and GABRP." (PMID 35846884, 2022). "Silibinin, a flavonolignan composed of two diastereomers (silibinin A and B), strongly inhibited the activity of the CD44 promoter in the prostate (PC-3M) and pancreatic cancer cell lines (BxPC-3 and PANC-1)." (PMID 35785191, 2022). "We recently identified that CAF promoted the enrichment of the stemness population through osteopontin (OPN) or secreted phosphoprotein 1 (SPP1) and CD44-mediated cellular cross-talk in pancreatic cancer cells." (PMID 36550571, 2022). "ASPN binds to CD44 in pancreatic cancer cells and activates the CD44/AKT/ERK-NF-kB signaling axis, which lead to EMT induction and increased migration and invasion." (PMID 36358747, 2022). "First of all, we systematically evaluated the two putative pancreatic cancer stem cells phenotypes ESA+CD24+CD44+ and CXCR4+CD133+ in all cell lines." (PMID 36142575, 2022). "The nanoparticles were functionalized with a mAb against CD44, a cell surface marker of stem cells, and were capable of efficiently binding and killing pancreatic cancer stem cells in vitro and targeting an orthotopic model of pancreatic cancer in vivo." (PMID 35626078, 2022). "CD44 promotes the epithelial-to-mesenchymal transition in pancreatic cancer via activation of Snail, which regulates the expression of membrane type 1 metalloprotease." (PMID 35846884, 2022). "CD44(+)/CD24(+) fractions from pancreatic tumors are enriched in sphere-forming cells, and nestin, which is a CSC marker of PDAC, had increased expression in the spheres of the three PDAC cell lines than in the non-sphere cells." (PMID 35629168, 2022). "Both CD44 and CD44V3 expression levels were associated with a poor prognosis in pancreatic cancer patients." (PMID 36292918, 2022). "In the current study, the regulatory roles of CD44 in pancreatic cancer progression and prognosis were investigated." (PMID 36292918, 2022). "In order to study the role of CD44 in the progression of pancreatic cancer, we first investigated the correlation between the prognosis and the expression level of CD44 in cancer tissues using the Kaplan–Meier Plotter." (PMID 36292918, 2022). "In this study, the specific mechanism by which the CDCA8 contributes to pancreatic cancer progression via the activation of CD44 was clarified, and CDCA8 knockdown inhibited the proliferation and metastasis of pancreatic cancer." (PMID 36358852, 2022). "Kaplan–Meier plots of overall survival (OS) and relapse-free survival (RFS) in pancreatic cancer patients were stratified according to their CD44 levels." (PMID 36292918, 2022). "The transcription factor Foxo3 is expressed a high level in CD44-positive cells from patients with pancreatic cancer and in PDAC cell lines such as Pan-1, Mia-Paca-2, and BxPC-3." (PMID 36605595, 2022). "Other studies confirmed our findings that CD44-positive drug resistant cancer stem-like cells isolated from pancreatic cancer cells formed larger colonies and spheroids." (PMID 35846884, 2022). "In this study, surface marker expressions for the pancreatic cancer stem cell-like population, namely CD44, CD24, and ESA for Panc1 cells and CD44, CD133, and EpCAM in MiaPaCa2 cells were investigated." (PMID 35634239, 2022).
pancreatic cancer (continued). "The histological images of the formed tumors reflected characteristics of pancreatic cancer, which is rich in stroma, and also contained CD44-positive cells as observed in vitro." (PMID 35505283, 2022). "Special attention will be paid to pancreatic adenocarcinoma (PDAC), where CD44 is well-known for contributing to pancreatic cancer cell plasticity, invasiveness and response to therapy." (PMID 35056160, 2022). "CD44+ CD24+ epithelialspecific antigen pancreatic cancer cells demonstrated stem cell properties such as self-renewal, tumorigenic capacity, maintenance of tumor growth, and resistance to chemo- or radiation therapy." (PMID 34094034, 2021). "Thereby, we identified CD44 as promising drug target for pancreatic cancer patients with high CFL1 expression." (PMID 33578795, 2021). "HA can achieve active tumor targeting by recognizing highly expressed CD44 on the surface of pancreatic tumors." (PMID 33643795, 2021). "This is further supported by in vitro and in vivo preclinical studies showing decreased migration and growth in pancreatic cancer cells after CD44 knockdown." (PMID 33578795, 2021). "According to the flow cytometry experiment, the number of CD44 positive (CD44+) pancreatic cancer cells, which are considered as cancer stem cell (CSC) characteristic indicators, was also enhanced." (PMID 34631547, 2021). "There is also evidence showing that CD44 positive cells play an important role in gemcitabine resistance in pancreatic cancer, distant metastasis, and aggressive behavior." (PMID 33921242, 2021). "That came in agreement with HA-SMA-NMS that effectively delivered CDF to the aggressive CD44+ stem-like pancreatic cancer cells and HA-TPGS-DOX that increased doxorubicin cytotoxicity in MCF-7/ADR." (PMID 33672756, 2021). "We isolated cancer stem cells (CSCs) from the human PANC-1 pancreatic cancer cell line as CD44+CD24+EpCAM+ cells." (PMID 34885233, 2021). "Confocal microscopy revealed that these PANC-1 CSC pancreatic cancer spheroids were labeled with antibodies against CD44, CD24, EpCAM." (PMID 34885233, 2021). "For example, overexpression of Notch1 and Notch2 has been correlated with increased expression of CD44 and EpCAM in pancreatic cancer (PDAC)." (PMID 34774101, 2021). "The significance of the CD44 co-receptor function has also been implied in the growth and maintenance of metastasis in pancreatic tumors." (PMID 34453639, 2021). "Another cell-surface glycoprotein, CD44 is a known prognostic biomarker and therapeutic target in pancreatic cancer." (PMID 33672926, 2021). "In human pancreatic cancers, CD44+CD24+ESA+ cells have been found to be enriched for cancer stem cells (CSCs) verified by testing the tumor initiating capability of those cells in vivo." (PMID 33924486, 2021). "Pancreatic cancer spheres were mechanically dissociated into single cells in a special cell disaggregation medium and sorted for CD44+CD24+EpCAM+ cells by means of flow cytometry." (PMID 34885233, 2021). "CD44 is a CSC marker in breast, prostate, colon, head and neck and pancreatic cancer, however CD44 also regulates T helper type 1 (Th1) cell survival and memory function, IL17 and IFN-γ production by T-cell." (PMID 33806296, 2021). "Flow cytometric analysis revealed that SNHG7 overexpression enhanced the fraction of CD44+ pancreatic cancer cells." (PMID 34631547, 2021). "High co-expression of CD44/CD133 and CD204 (MSR1) was associated with short overall survival in another study on pancreatic carcinoma." (PMID 34281234, 2021). "Amongst several molecules that have been extensively described and investigated for their possible roles in pancreatic carcinoma progression and tumourigenesis, CD44 is the most significant." (PMID 34944493, 2021). "As a result, ductal (CA2, CK19, and SOX9)/pancreatic cancer (EpCAM and CD44) markers decreased and acinar markers (SYP and PTF1A) increased by inhibitor treatment in KiPCs." (PMID 33233448, 2020).
pancreatic cancer (continued). "Compared with PCs and iPCs, the gene expression levels of some pancreatic cancer markers (epithelial cell adhesion molecule (EpCAM), CD44, CD133, and c-MET) were significantly increased in KiPCs." (PMID 33233448, 2020). "Corresponding to the meta-analysis enrolling a total of 583 pancreatic cancer patients, high level of CD44 was correlated with adverse 5-year OS and advanced TNM stage, whereas did not associate with tumor size and tumor differentiation." (PMID 33303029, 2020). "Upregulation of CD44 is correlated with tumor progression and the metastatic phenotype in many cancers, including pancreatic cancer." (PMID 31963309, 2020). "E3330 was able to suppress CD44 expression in pancreatic cancer cells, promoting a direct consequence for cell migration." (PMID 32599967, 2020). "Numerous molecular markers, including Cd24, Cd44, Prom1 (Cd133), and other genes, have been applied in order to define pancreatic cancer stem cells (CSCs)." (PMID 32429174, 2020). "It has been reported that pancreatic cancer patients with high CD44 expression had significantly shorter overall survival than those with low CD44 expression." (PMID 32576817, 2020). "In a previous report, pancreatic cancer cells expressing CD24/CD44 or CD133 functioned as CSCs and exhibited tumorigenesis and chemoresistance." (PMID 32266133, 2020). "Pancreatic cancer cells surviving 6 days of continuous GEM treatment expressed higher levels of CSC markers like CD44 and CD133 along with EMT regulators like Snail and Slug." (PMID 31139022, 2019). "In agreement with our results, these CD133+CD44+ cancer cells have been characterized in several highly metastatic tumors such as CRCs, HCCs, pancreatic cancers, and gallbladder carcinoma." (PMID 31139149, 2019). "Genetic ablation of KLF4 in pancreatic cancer cells isolated from KLF4 flox/flox mice significantly increase CD44 expression." (PMID 29747682, 2018). "In pancreatic cancer cell lines expressing CD44, the isoform 3A of the enzyme phosphodiesterase (PDE3A) is highly expressed." (PMID 30563268, 2018). "To further demonstrate the effect of FL118 on stem-like, drug-resistant cancer cells, we isolated the CD44 stem cell marker-positive pancreatic cancer cell population from the drug-resistant PANC1 cells." (PMID 30285798, 2018). "Treatment of mice harboring orthotopically implanted pancreas tumors with a CD44 neutralizing antibody reduces tumor growth, metastasis, and postradiation recurrence." (PMID 29747682, 2018). "According to this literature, EGCG seems to act by downregulating CD44 expression in tumours, like non-small cell lung cancer and pancreatic cancer." (PMID 30563268, 2018). "Our lab also observed higher ERK1/2 activation in CD44-positive pancreatic cancer cells than in its counterpart of CD44 knock-down clones (unpublished data)." (PMID 29747682, 2018). "In agreement with isoform switching, our lab recently demonstrated in pancreatic cancer cells that an EMT phenotype was dependent on upregulation of CD44 expression with CD44s being the most prevalent isoform." (PMID 29747682, 2018). "Treatment of mice harboring orthotopically implanted pancreas tumors with a CD44 neutralizing antibody (H4C4) reduced tumor growth, metastasis, and postradiation recurrence." (PMID 29747682, 2018). "In multiple types of cancers, including breast, colon, prostate and pancreatic cancer, CD44 is identified as a marker of CSCs8." (PMID 28507327, 2017). "Here, we demonstrated that CD44 expression is higher in patients with pancreatic cancer compared to those with chronic pancreatitis." (PMID 28659655, 2017). "As CD44+CD24+ESA+ or CD133+ pancreatic cancer cells exhibited stem cell properties, flow cytometry demonstrated the presence of a rare CSCs population." (PMID 29254186, 2017). "The subpopulations of pancreatic cancer cells that express CD44 and CD24 display CSC-like properties." (PMID 29179494, 2017).